ENSG00000285095 (novel transcript)
Synonyms: LOC112268208
Gene: Long non-coding RNA gene on chromosome 18 (32,470,210 to 32,745,567, forward strand). Ensembl gene ENSG00000285095.
Gene Ontology:
Biological process: SRP-dependent cotranslational protein targeting to membrane, signal sequence recognition
Cellular component: signal recognition particle, endoplasmic reticulum targeting